FNBP1 (formin binding protein 1)
Description:
May act as a link between RND2 signaling and regulation of the actin cytoskeleton (By similarity). Required to coordinate membrane tubulation with reorganization of the actin cytoskeleton during the late stage of clathrin-mediated endocytosis. Binds to lipids such as phosphatidylinositol 4,5-bisphosphate and phosphatidylserine and promotes membrane invagination and the formation of tubules. Also enhances actin polymerization via the recruitment of WASL/N-WASP, which in turn activates the Arp2/3 complex. Actin polymerization may promote the fission of membrane tubules to form endocytic vesicles. May be required for the lysosomal retention of FASLG/FASL.
Synonyms: FBP17; KIAA0554
Tractability: Antibody: its Gene Ontology location is reachable by antibodies, with high confidence; UniProt places it where antibodies can reach, with medium confidence; the Human Protein Atlas places it where antibodies can reach. PROTAC: ubiquitination databases record sites on it; its protein half-life has been measured.
Gene: Protein-coding gene on chromosome 9 (129,887,179 to 130,043,238, reverse strand). Ensembl gene ENSG00000187239.
Subcellular location: Cytoplasm; Cytoplasm, cytoskeleton; Cytoplasm, cell cortex; Lysosome; Cytoplasmic vesicle; Cell membrane; Membrane, clathrin-coated pit
Subcellular location (Human Protein Atlas): Plasma membrane; Vesicles
Pathways (Reactome):
Signal Transduction: CDC42 GTPase cycle; RHOJ GTPase cycle; RHOQ GTPase cycle; RND2 GTPase cycle
Vesicle-mediated transport: Clathrin-mediated endocytosis
Gene Ontology:
Molecular function: identical protein binding; protein binding
Biological process: endocytosis; signal transduction
Cellular component: plasma membrane; cytosol; cell cortex; clathrin-coated pit; cytoplasm; cytoplasmic vesicle; cytoskeleton; lysosome
Genetic constraint (gnomAD): Loss-of-function variants: 20 observed, 63.6 expected, observed/expected ratio (o/e) 0.31, 90% interval 0.22 to 0.46. The upper end of that interval is the gene's LOEUF score, 0.46, which puts it in group 2 of 6, group 1 being the genes least tolerant of losing a copy. Missense variants: 550 observed, 666.71 expected, observed/expected ratio (o/e) 0.82, 90% interval 0.77 to 0.88. Synonymous variants: 232 observed, 234.28 expected, observed/expected ratio (o/e) 0.99, 90% interval 0.89 to 1.1.
Homologues: Orthologues: macaque FNBP1 (99% identical), chimpanzee FNBP1 (97% identical), dog FNBP1 (95% identical), pig FNBP1 (94% identical), rat Fnbp1 (94% identical), mouse Fnbp1 (94% identical), guinea pig FNBP1 (87% identical), rabbit FNBP1 (83% identical), tropical clawed frog fnbp1 (82% identical), zebrafish fnbp1b (72% identical), zebrafish fnbp1a (69% identical), Drosophila melanogaster Cip4 (35% identical), and 3 more. Paralogues in human: FNBP1L (56% identical), TRIP10 (50% identical).